MMP2 (matrix metallopeptidase 2)
Diseases named in the same sentence as MMP2 in open-access papers (continued):
Sharing a sentence is not in itself a finding about the gene and the disease.
colorectal cancer (continued). "NK cells from colorectal cancer patients are polarized toward a pro-angiogenic phenotype, and they express angiogenin, MMP2 and MMP9." (PMID 34638439, 2021). "Based on their relevance in colorectal cancer invasion, we also evaluated the mRNA expression of the matrix metalloproteinase 2 (MMP2) and its inhibitor TIMP2." (PMID 34201494, 2021). "Accordingly, the reduced expression of the MMP2 inhibitor TIMP2 correlates with colorectal cancer invasion and a worse prognosis." (PMID 34201494, 2021). "In humans, several malignant tumors, such as pancreatic adenocarcinoma, metastatic renal cell tumor and colorectal cancer, can increase blood MMP‐2, ‐7, or ‐9 concentrations." (PMID 33274549, 2021). "MMP-2 and MMP-9 are known as type IV collagenase and are increased in CRC patients and are associated with colorectal cancer progression." (PMID 34502094, 2021). "In line with this, cofilin-1 silencing reduces colorectal cancer cell migration and invasion rates, as well as MMP2 activity." (PMID 34066419, 2021). "It has been demonstrated that MMP2 is upregulated in invasive colorectal cancers and participates in the metastatic process by degrading β1 integrins, thereby decreasing cell adhesion and enhancing their motility." (PMID 34201494, 2021). "Increased expression of MMP-2 and MMP-9 in normal tumor-free mucosa adjacent to colorectal tumors was independently associated with poor prognosis in colorectal cancer patients." (PMID 34502094, 2021). "MMP-2 and MMP-9 were increased in the serum of colorectal cancer patients, and their diagnostic sensitivity was higher than that of other biomarkers currently used in clinical practice, such as CEA and CA19-9." (PMID 34502094, 2021). "Celecoxib suppressed tumor growth and angiogenesis, which mediated a decrease in the amount of CD34+ cells, inhibition of COX-2, PGE2 synthesis, and VEGF and MMP-2 mRNA expression in a mouse model of colorectal cancer." (PMID 34209679, 2021). "In colorectal carcinoma (CRC), binding of HA by CD44v6 causes the secretion of MMP-2 and -9, leading to changes in the ECM." (PMID 33540535, 2021). "For example, multiplex quantification of ovarian and colorectal cancer biomarkers: matrix metalloproteinases 2 and 7 (MMP-2 and MMP-7, respectively) was performed by an electrode array modified with peptide-specific substrates for MMP-2 and MMP-7." (PMID 32585936, 2020). "It is important in the initiation of colorectal cancer and SATB1 expression in colorectal cancer is associated with the expression of S100A4, MMP2, NF-kB, PCNA, cyclin D1 and β-catenin." (PMID 33356851, 2020). "Eleven tagging SNPs in four genes (EFNB2, MMP2, JAG1 and KDR) were significantly associated with overall survival of colorectal cancer patients." (PMID 32751332, 2020). "Our data are in line with a previous study showing that inhibiting ERK1/2 activity by U0126 significantly suppresses the transcription activity of MMP-2 by inhibiting the phosphorylation of hnRNPK and its nuclear translocation in colorectal cancer (CRC) cells." (PMID 30971268, 2019). "Among the top 10 deregulated genes, MMP2 (Matrix Metallopeptidase 2) is well known for its role in colorectal cancer invasion and EPSTI1 (Epithelial stromal interaction 1) and MPO (Myeloperoxidase) are related to tumor development." (PMID 30987352, 2019). "In the context of colorectal cancer, the mean activity of MMP2 was found to be around ten times higher in tumor tissue compared to normal mucosa." (PMID 30473751, 2018). "In colorectal cancer HT-29 cells, treatment with gefitinib reduced the expression of MMP-2, MMP-9, and VEGF-A, which are involved in cancer cell invasiveness." (PMID 30187356, 2018). "A study demonstrated an increase in plasma MMP-2 in colorectal cancer over benign colonic pathology." (PMID 29949618, 2018). "Similar observation was reported in colorectal carcinoma cells, where a flavonoid, myricetin, inhibited MMP-2 activity and cell invasion." (PMID 29891015, 2018).
colorectal cancer (continued). "In different study populations higher circulating levels of MMP-1, MMP-2 and MMP-3 were strongly associated with all-cause mortality in patients with colorectal cancer, myocardial infarction or heart failure." (PMID 28446168, 2017). "A recent study demonstrated that APOBEC3G down regulates miR-29 expression and hampers miR-29 activity in repressing MMP2, which promotes hepatic metastasis of colorectal cancer." (PMID 28903341, 2017). "For instance, in colorectal cancer, MMP2 mRNA is detected in higher levels in unaffected tissue surrounding metastatic tumors." (PMID 29164121, 2017). "Consistent with previous studies, we showed that the HSPA5 increased MMP2 mRNA production involved in JNK activities in colorectal cancer cells." (PMID 27034162, 2016). "We randomly chose 87 colorectal cancer tissue samples to analyze the expression levels of B7-H3, MMP2 and MMP9 by immunohistochemistry." (PMID 27145365, 2016). "Lastly, our results suggested FOXM1 facilitated the activities of MMP2 and 9 associated with HSPA5 in colorectal cancer cells." (PMID 27034162, 2016). "In our study, we revealed that both MMP-9 and MMP-2 were co-expressed with B7-H3 in colorectal cancer tissue; the correlation coefficients were 0.7492 and 0.5643, respectively." (PMID 27145365, 2016). "The study aimed to investigate the expression, clinical significance and function of eIF4E, VEGF-C, E-cadherin, and MMP2 in colorectal cancer and determine the potential of eIF4E, VEGF-C, E-cadherin and MMP2 as indicators of colorectal cancer." (PMID 27907907, 2016). "Inhibition of PARP with 5-AIQ down regulates the expression of MMP-9 and MMP-2 as well as their activities via decreasing NF-kB expression, facilitating the suppression of tumor metastasis in colorectal cancer." (PMID 27659937, 2016). "Lastly, our results suggested FOXM1 facilitated the activities and expressions of MMP2 and 9 associated with cell-surface HSPA5 in colorectal cancer cells." (PMID 27034162, 2016). "Cox regression analysis of PXN, Bcl-2, pBcl-2-S87 and MMP2 expressions in patients with colorectal cancer." (PMID 25826088, 2015). "The serum levels of MMP-2 correlated significantly with serum levels of TIMP-2 in colorectal cancer patients (p < 0.001) and intensity of this protein expression in inflammatory (p = 0.012) and normal colorectal cells (p = 0.039)." (PMID 24395652, 2014). "Numerous studies have demonstrated a strong correlation between MMP-2/9 expression and migration/invasion in human colorectal cancer cells." (PMID 23506655, 2013). "In several studies over-expression (Cyclin D1, NF-κB, PCNA, MMP-2) or loss of expression (Bcl-2, APC) of these molecules have been found to be associated with more aggressive tumor growth in colorectal cancer." (PMID 23326301, 2013). "The median protein level of MMP-2 and MMP-9 in the normal mucosa of the 198 colorectal cancer patients was 4.8 ng mg−1 protein (range, 0–30.5) for MMP-2 and 3.2 ng mg−1 protein (range, 0.2–164.7) for MMP-9." (PMID 22472880, 2012). "We previously reported that MMP-2 genotype and high levels of tumour MMP-2 are associated with a poor survival in colorectal cancer patients." (PMID 22472880, 2012). "The gelatinases MMP-2 and MMP-9 are implicated in the process of colorectal cancer progression, angiogenesis and metastasis." (PMID 22472880, 2012). "Previously we showed that MMP-2 in the intestinal mucosa of colorectal cancer patients is predominantly expressed in the submucosal extracellular matrix and MMP-9 in the mucosal macrophages and neutrophils." (PMID 22472880, 2012). "In the present study, we evaluated the association between, and the prognostic relevance of tissue protein levels of MMP-2 and MMP-9 and their gene promoter single-nucleotide polymorphisms (SNPs) in a cohort of 215 Dutch colorectal cancer patients." (PMID 18506186, 2008).
colorectal cancer (continued). "The prognostic significance of single-nucleotide polymorphisms (SNPs) and tumour protein levels of MMP-2 and MMP-9 was evaluated in 215 colorectal cancer patients." (PMID 18506186, 2008). "MMP-2 and MMP-9 have been implicated to play a role in colorectal cancer progression, invasion and metastasis in animal models and patients." (PMID 16916471, 2006). "MMP-2 and MMP-9, members of the MMP family, are strongly linked to colorectal cancer metastasis." (PMID 40777130, 2025). "In the phase of adenoma development, increased expression of MMP-1, MMP-3, MMP-7, and MMP-9 was observed, and subsequently, at the stage of colorectal cancer invasion, other MMPs, including MMP-2, MMP-8, MMP-10, MMP-12, MMP-13, MMP14, and MMP-21 are activated and overexpressed." (PMID 39337393, 2024). "As colorectal cancer progression involves the activity of MMP-2 and MMP-9, we investigated whether treatment with aronia extracts could affect gelatinase activity in SW-480 and HT-29 cells." (PMID 39683504, 2024). "However, some researchers reported that MMP-2 is highly prognostic for colorectal cancer survival vs. MMP-9 as it is significantly increased in patients with lymph node metastasis compared to those without." (PMID 37509428, 2023). "CRP could potentially promote CEA, MMP1 and MMP2 by stimulating LOX-1 receptors in colorectal cancer." (PMID 38071306, 2023). "Therefore, this study aimed to investigate the improvement effect of NAC on QOE in suppressing colorectal cancer migration and invasion, through the ICAM-1 and MMP-2 associated with iNOS/eNOS suppression." (PMID 37575276, 2023). "MMP-2 and MMP-9 promoter polymorphisms can affect mRNA and protein expression levels by modifying transcriptional activity, eventually leading to the development of several types of cancer, including breast, lung, esophageal, and colorectal cancer." (PMID 37445754, 2023). "In colorectal cancer, as well as in other solid tumors, both the plasma MMP-2 and -9 levels are reported to be related to clinical staging and could potentially represent an indicator of invasion or metastasis." (PMID 37509428, 2023). "Moreover, a combined treatment with an ERK inhibitor (U0126) and baicalein against colorectal carcinoma (CRC) led to the synergistic reduction of MMP-2/9 expression, which is responsible for the anti-metastatic effect in CRC cells." (PMID 36902160, 2023). "Studies have also shown that high expression of eIF4E in invalids with colorectal cancer predict high risk of hepatic metastases and their related mechanism may be partly by the regulation of the levels of VEGF, cyclin D1, MMP-2, and MMP-9." (PMID 36118897, 2022). "Single-cell RNA sequencing (scRNA-seq) analysis from colorectal cancer patients showed that SPP1+ TAMs expressing syndecan-2 (SDC2) were more likely to interact with CAFs expressing MMP-2 through the combination of SDC2 and MMP-2 to promote the activation of CAFs and tumor tissue fibrosis." (PMID 35898884, 2022). "As colorectal cancer progression involves MMP-2/9 activity that is up-regulated by IL-6, we first analyzed whether the treatment with rIL-6 alone or after the LPE pretreatment could affect the gelatinase activity in T88 and T93 cells." (PMID 34885656, 2021). "DLX6-AS1 can bind miR-203a to promote the MMP-2 pathway in colorectal cancer." (PMID 33216728, 2020). "Four tagging SNPs (none in high LD with r2 < 0.8) in the region of MMP2 were significantly associated with overall survival of colorectal cancer patients." (PMID 32751332, 2020). "AMPK, an upstream regulator of MMP2, could decrease the migration and invasion of colorectal cancer through inhibition of MMP2." (PMID 33008449, 2020). "Up-regulation of MMP2 under hypoxia requires ROS generation in colorectal cancer cells." (PMID 32499699, 2020). "Thus, rHct-S3 decreases the migratory activity of colorectal carcinoma HT-29 cells by the inhibition of MMP-2 and MMP-9 and induces the apoptosis via the activation of caspase-3." (PMID 33348592, 2020).
colorectal cancer (continued). "In addition, increased transcription activity and mRNA level of MMP2 were shown in hnRNP‐K enhancing colorectal cancer cell lines." (PMID 30444036, 2019). "The phenomenon of tumor promoting (oncogenic) activity of the MMP2 was previously demonstrated in colorectal cancer, where elevated MMP2 mRNA levels in “healthy” tissue surrounding the lesion were significantly higher in patients with metastatic cancer than in non-metastatic lesions." (PMID 31921636, 2019). "In their 32 colorectal cancer patients, MMP-2 and MMP-9 seemed to correlate with more advanced stage; however, by this method, their results may be, at least in part, uncertain." (PMID 29929486, 2018). "Among 108 patients with colorectal cancer, 75.9% (82/108) of cases were MMP-2 positive." (PMID 27907907, 2016). "Moreover, we observed statistically significantly positive correlations between FOXM1 and MMP2 mRNA expression, between HSPA5 and MMP2 in colorectal cancer tissue specimens." (PMID 27034162, 2016). "Moreover, B7-H3 had a positive relationship with MMP2 expression in colorectal cancer, y = 0.1843x+1.3442 R2 = 0.5643." (PMID 27145365, 2016). "More interestingly, eIF4E also regulates the expression of MMP-2 in colorectal cancer." (PMID 27907907, 2016). "In the present study, we provided evidence from cells, xenograft tumors, and human tumors to demonstrate that ERK activation by PXN promoted tumor aggressiveness and led to poor patient outcome in colorectal cancer and that this promotion occurs via increased pBcl-2-S87-mediated MMP2 expression." (PMID 25826088, 2015). "A study suggests that genetic variations in the MMP2 (rs2285053) might be potential predictors of distant metastasis-free survival after curative surgery in patients with colorectal cancer." (PMID 25906101, 2015). "In colorectal cancer, the positive reaction was observed in 23.6 % of cases in cancer cells and 50 % of inflammatory infiltrate cells, whereas in normal colorectal tissue surrounding tumor nests, the presence of MMP-2 was observed only in one case." (PMID 24395652, 2014). "However, little is known about the comparison of the levels of MMP-2 and TIMP-2 in the sera of CRC patients with an expression of MMP-2 and its inhibitor in colorectal cancer tissue." (PMID 24395652, 2014). "Our research therefore suggests that this Chinese Herbal medicine, YQFS, could inhibit migration/invasion of colorectal cancer by down-regulating MMP-2/9 via inhibition of the ERK/MAPK signaling pathway." (PMID 23506655, 2013). "This is a clear indication that MMP-2 is a key factor in the regulation of cell migration, however it should not be ruled out that other ECM degrading MMPs such as MMP-1, MMP-7, MMP-9 and MMP-13 have been shown be associated with Colorectal cancer progression." (PMID 24130681, 2013). "MMP2 has been shown to be important for metastasis in colorectal cancer." (PMID 22912670, 2012). "Also in colorectal cancer, the serum levels of the MMP-2-TIMP-2 complex are found to be lower than in healthy controls." (PMID 20671952, 2010). "Our ELISA-derived MMP-2 data correspond very well with a recent immunohistochemical study in a group of 351 colorectal cancer patients, showing that high expression of MMP-2 in malignant epithelium as well as in the surrounding stroma was associated with reduced survival." (PMID 18506186, 2008). "Despite the absence of a correlation between promoter-located SNP −1306C>T in the MMP-2 gene with tumour MMP-2 levels, both parameters were significantly associated with survival, indicating MMP-2 as a consistent independent prognostic factor in colorectal cancer." (PMID 18506186, 2008). "Also in our present cohort of colorectal carcinoma patients, we found that MMP-2 and MMP-9 levels within the tumours are of significance to survival." (PMID 18506186, 2008).
colorectal cancer (continued). "Therefore, we classified colorectal cancer into colon and rectal cancer and examined differences in the expression of MMP-2, MMP-9, TIMP-1, TIMP-2, uPA, uPAR and PAI-1 between colon and rectal cancer." (PMID 16916471, 2006). "Finally, we evaluated whether PMPs can stimulate colorectal cancer cell invasiveness by enhancing MMP-2/MMP-9 levels and activity via the p38MAPK pathway." (PMID 36882818, 2023). "Taken together, these results verified that AAM effectively inhibits migration and VM formation by suppressing ROS/HIF-1α/MMP2 pathway in colorectal cancer under hypoxic condition, suggesting AAM could serve as a therapeutic agent to inhibit VM formation in human colorectal cancer." (PMID 32499699, 2020). "And we demonstrated that overexpression of β3GnT8 increased the expression of HG-CD147 in colorectal cancer cells, and knockdown of β3GnT8 reduced HG-CD147 expression, suggesting that β3GnT8 might regulate the expression of MMP2 through altering CD147 glycosylation in colorectal cancer." (PMID 29875690, 2018). "Additionally, FOXM1 has been found to increase colorectal cancer migration and invasion by regulating a various signal pathways, such as urokinase-type plasminogen activator receptor (uPAR) and matrix metalloproteinase 2 and 9 (MMP2 and 9) signaling pathway." (PMID 27034162, 2016). "In conclusion, this study shows that increased MMP-2 and MMP-9 protein expression in normal mucosa at some distance of colorectal tumours is strongly related to the course of disease, that is, independently associated with a poor prognosis of colorectal cancer patients." (PMID 22472880, 2012). "A recent study has shown that in colorectal cancer (CRC) cells, TYRO3 undergoes intermembrane cleavage via a different mechanism involving MMP2 (or gelatinase-A)." (PMID 40044635, 2025). "Olaparib alone reduced mRNA expression levels of MMP2 and MMP9 in oral carcinoma cell lines and, combined with bevacizumab, was found to reduce the serum levels of MMP9 in advanced colorectal cancer." (PMID 39859407, 2025). "Due to the recognized functions of MMP-2 and MMP-9 in extracellular matrix degradation and colorectal cancer progression, these gelatinases were chosen for examination." (PMID 41154590, 2025). "In our experimental conditions, blueberry pomace extract most effectively inhibited MMP-1, MMP-2, and MMP-3 in C2BBe1 colorectal cancer cells." (PMID 39200479, 2024). "It fights against cancer cells through several pathways, including (a) control of MMP-2 and MMP-9 activities and (b) reduction of MMP-2 protein production in colorectal cancer cells (COLO 205)." (PMID 38672151, 2024). "In another study, quercetin in combination with Lycopodium clavatum extract resulted in a significant downregulation of MMP-2 and MMP-9 activities, as tested by gelatin zymography in colorectal cancer Colo-320 cells." (PMID 39683504, 2024). "TFAP2A overexpression in ovarian and colorectal cancer cells displays epithelioid morphology, possibly because TFAP2A binds to the promoters of E-cadherin and MMP2/9, resulting in increased E-cadherin expression but decreased MMP2/9 levels due to SP1 binding." (PMID 37291585, 2023). "Gomisin A can also reduce the levels and activities of matrix metalloproteinase (MMP)-2 and MMP-9, and improve the lung metastasis of colorectal cancer cells by reducing the cell survival and metastasis ability of colorectal cancer cells." (PMID 37560060, 2023). "DKC1 has been shown to regulate the NF-κB/MMP-2 pathway in ccRCC, and improve HIF-1α transcription levels by binding its promoter region in colorectal cancer." (PMID 38082360, 2023). "MnTE-2-PyP inhibited the Smad2/3 signaling pathway and the expression of matrix metalloproteinase 2 (MMP-2) and 9 (MMP-9) in colorectal cancer cells, reducing TGF-β-induced EMT and thus invasion of the colorectal and other cancer cells." (PMID 37049670, 2023).